INS (insulin)
Diseases named in the same sentence as INS in open-access papers (continued):
Sharing a sentence is not in itself a finding about the gene and the disease.
type 2 diabetes (continued). "Correction of poor glycemic control and use of insulin leads to increased skeletal muscle mass in Japanese patients with Type 2 diabetes." (PMID 36942499, 2023). "This element is involved in insulin storage, synthesis, and release, suggesting the key role of this microcomponent in the progression of type 2 diabetes, atherosclerosis, and metabolic syndrome (MS)." (PMID 36839370, 2023). "In the NT group, antidiabetic medications (insulin or metformin) were taken by 10 of 12 patients with Type 1 and/or Type 2 diabetes, and 2 of 3 patients with gestational diabetes." (PMID 37628909, 2023). "Basal insulin combined oral therapy consisting of insulin and oral anti-diabetic drugs (OADs) is recommended for type 2 diabetes uncontrolled on OADs." (PMID 36624650, 2023). "The fixedratio combinations with molecules such as insulin degludec + liraglutide, and insulin glargine + lixisenatide have proven useful in intensifying treatment of individuals with type 2 diabetes." (PMID 37185053, 2023). "After internal and external review, two strong recommendations, six conditional recommendations, and one qualifying statement were made for insulin‐naive adult patients with type 2 diabetes." (PMID 37088916, 2023). "The addition of a GLP-1 RA reduced HbA1C, weight, and insulin requirements in this cohort of patients with type 2 diabetes on insulin." (PMID 37589043, 2023). "One of the key players of MeS is the disruption of the glucose–insulin axis, which is a precursor of type 2 diabetes." (PMID 38201945, 2023). "Patients with type 2 diabetes were divided on the basis of their plasma insulin response to oral glucose into hyper-insulinemic and normo-insulinemic groups." (PMID 37762244, 2023). "In this study, we found that 341 out of 779 (43.8%) subjects with insulin-treated type 2 diabetes presented with hyperinsulinemia, of whom 113 subjects (33.1%) had real hyperinsulinemia, and the remaining subjects (66.9%) were IAs-positive." (PMID 37324170, 2023). "More than 90% of patients with type 1 diabetes were treated with insulin, and in patients with type 2 diabetes the most commonly used drugs was metformin (379, 69.41%), followed by DPP-4 (204, 37.36%) and SGLT2 (198, 36.2%)." (PMID 36997918, 2023). "Thiazolidinediones (TZDs) are synthetic PPARγ ligands currently used in the treatment of type 2 diabetes for their ability to induce insulin sensitization and improve glycemic control." (PMID 37048080, 2023). "Hypoglycemia remains a daily threat for most people with type 1 diabetes (T1DM) or insulin-treated type 2 diabetes (T2DM)." (PMID 36930585, 2023). "Type 2 diabetes mellitus (T2DM) is an insulin resistance disease, which is a metabolic disorder caused by insufficient insulin secretion in the body." (PMID 38152330, 2023). "Apart from its anti-oxidant properties, IPA can inhibit the growth of Mycobacterium tuberculosis (Mtb) and can stimulate the secretion of incretin (GLP-1) to improve insulin secretion and protect against type 2 diabetes progression." (PMID 36890518, 2023). "We determined idealistic, realistic, and unrealistic expectations about metformin, insulin, and glyburide in persons with type 2 diabetes in primary care." (PMID 36817935, 2023). "Obese and type 2 diabetes patients display “metabolic inflexibility” manifested by impaired insulin-stimulated skeletal muscle glucose oxidation." (PMID 37802398, 2023). "Recent clinical guidance recommends routine islet-autoantibody testing when type 1 diabetes is clinically suspected or in the context of rapid progression to insulin therapy after a diagnosis of type 2 diabetes." (PMID 37728732, 2023). "Thirty two Latino adolescent males with obesity aged 14–17 years with a family history of type 2 diabetes underwent a frequently sampled glucose tolerance test (FSIVGTT) to measure insulin sensitivity." (PMID 37864156, 2023).
type 2 diabetes (continued). "For type 2 diabetes insulin injection and different medicine types like Alpha-glucosidase inhibitors, biguanides, etc. are used." (PMID 38264582, 2023). "Chronic sleep deprivation can lead to hormonal dysregulation and, thus, affect insulin sensitivity, contributing to the development of metabolic disorders such as type 2 diabetes and obesity." (PMID 37445852, 2023). "Type 2 diabetes mellitus (T2DM) is a metabolic disease largely characterized by impaired insulin secretion and action." (PMID 37498817, 2023). "Carnosine (β-alanyl-L-histidine) has been suggested to improve insulin sensitivity in type 2 diabetes patients, and a growing evidence of animal studies indicate a protective role of carnosine in diabetes." (PMID 36681701, 2023). "Adults with type 2 diabetes, requiring insulin treatment, on maximum tolerated dose of 2 or more oral antidiabetic drugs with HbA1c > / = 7.5% (58 mmol/mol) on 2 occasions." (PMID 37237318, 2023). "The two main types of this disease arise from either lack or decreased insulin production, known as type 1 diabetes (T1D), or increased resistance to this hormone action, designated as type 2 diabetes." (PMID 37958659, 2023). "The methylation status of the insulin gene was related to changes in LDL-c after an intervention with inulin agave (10 g/d) over 2 months in patients with type 2 diabetes." (PMID 37836535, 2023). "From the measurements carried out, a significant decrease in immunoreactive insulin was found in group 1, the group with obesity and type 2 diabetes, with the daily intraperitoneal application of WAY163909 (1 mg/kg), p < 0.01." (PMID 37190510, 2023). "In muscles, the quickest sign of type 2 diabetes is the onset of skeletal muscle insulin insensitivity." (PMID 38094528, 2023). "In premenopausal women, oestrogen protects from type 2 diabetes by increasing insulin sensitivity and glucose-stimulated insulin secretion, and mitigating beta cell apoptosis." (PMID 36897358, 2023). "Islets obtained from type 2 diabetic patients showed disrupted mitochondrial structure, reduced ATP levels, and decreased amounts of insulin granules, with a consequent reduction in insulin secretion." (PMID 37762083, 2023). "Pathologically, leptin resistance and decreased sensitivity to leptin receptors depolarize islet β cells and promote insulin secretion, resulting in hyperinsulinemia and type 2 diabetes." (PMID 36998473, 2023). "By contrast, impairments in cellular signal transduction and in insulin actions in response to insulin stimulation—labeled as IR —compromise glucose control leading to the development of Type 2 diabetes (T2DM)." (PMID 37513538, 2023). "Baseline clinical and biochemical characteristics of subjects with type 2 diabetes with non-insulin and insulin treatment." (PMID 37324170, 2023). "In skeletal muscles of type 2 diabetes subjects, insulin-resistant offspring of type 2 diabetes subjects, and obese individuals, disturbance of mitochondrial respiration was observed when compared to lean normal controls." (PMID 37762318, 2023). "Patient-facing, voice-based conversational AI applications can help patients with type 2 diabetes quickly achieve basal insulin dose optimization." (PMID 38039007, 2023). "The most common type of DM is type 2 diabetes (T2DM), which is usually associated with incomplete function of insulin." (PMID 37316931, 2023). "In this RCT, 5047 patients with type 2 diabetes received either liraglutide, insulin glargine, glimepiride or sitagliptin in addition to metformin." (PMID 37542009, 2023). "Taken together, classical conditioning with intranasal insulin has a wide range of potential positive effects for patients with diabetes type 2." (PMID 37234022, 2023). "Although insulin and glucagon play opposite regulatory roles both in normal metabolic homeostasis and dysfunction in type 2 diabetes, PWS mice are remarkable in having low blood levels of both insulin and glucagon." (PMID 37068109, 2023).
type 2 diabetes (continued). "Obesity is characterized by the presence of non-esterified fatty acids (NEFAs) released from adipose tissue, which contributes to insulin resistance and β-cell dysfunction, resulting in Type 2 diabetes." (PMID 37133312, 2023). "There were 58.9% type 2 diabetes, 41.1% type 1 diabetes, and 71.9% who received therapy with insulin injections." (PMID 37398721, 2023). "Type 2 diabetes affects the ability of insulin from stimulating glucose transport in skeletal muscles by diminishing and disrupting GLUT4 translocation to the cell surface." (PMID 37170065, 2023). "Improved blood glucose levels, increased insulin sensitivity, prevention or delay of type 2 diabetes development, and decreased glucose concentration are all benefits of T2DM patients engaging in regular exercise." (PMID 37964349, 2023). "This hormone also improves insulin sensitivity and increases fatty acid metabolism, and its low level correlates with type 2 diabetes, dyslipidemia, cardiovascular disease, and obesity." (PMID 38004222, 2023). "They focused on patients with both type 1 and type 2 diabetes with different treatment modalities (insulin pump, multiple daily insulin injections, oral hypoglycemic agents, GLP-1 agonists) and different glucose monitoring methods (CGM, FGM, SMBG)." (PMID 37685740, 2023). "Type 2 diabetes (T2D) is classically characterized by chronic hyperglycemia, due to increased hepatic glucose production, insulin resistance, and altered insulin production and secretion." (PMID 37233701, 2023). "An elevated proinsulin-to-insulin ratio in the blood has been postulated as a potential marker of type 2 diabetes for more than 20 years." (PMID 38020157, 2023). "Both MUP‐1 and OSTN are shown to be related to insulin sensitivity in an inverse way in type 2 diabetic rodent models." (PMID 37170065, 2023). "This study aimed to investigate the sustained safety and efficacy of insulin treatment simplification with IDegLira in patients with type 2 diabetes and an HbA1c ≤ 7.5% (58 mmol/mol) during a 12‐month follow‐up." (PMID 36461758, 2023). "In type 2 diabetes, propionate acts locally on tissues, improving insulin sensitivity, suppressing cholesterol synthesis, and lowering the risk of cardiovascular disease." (PMID 38371896, 2023). "In patients with type 2 diabetes, pancreatic beta cells progressively degenerate and gradually lose their ability to produce insulin and regulate blood glucose." (PMID 37813862, 2023). "Type 2 diabetes develops when the pancreas cannot produce enough insulin or when the insulin-sensitive tissues become resistant to insulin." (PMID 37215099, 2023). "The skeletal muscles of type 2 diabetic patients have been reported to contain fewer mitochondria compared to those of age-matched insulin-sensitive individuals." (PMID 36860368, 2023). "In HFD‐fed mice, both total β‐catenin expression and insulin‐stimulated β‐cateninS552 phosphorylation were lowered; however, in men with type 2 diabetes, only β‐catenin phosphorylation was reduced." (PMID 36807886, 2023). "The influence of GABA receptors in pancreatic islets contributes to decreased insulin secretion in type 2 diabetes, and GABA supplementation has been reported to increase insulin secretion." (PMID 37509868, 2023). "During the development of type 2 diabetes (T2D), the pancreatic beta cell mass initially increases to maintain glucose homeostasis under chronic nutrient oversupply and peripheral insulin resistance conditions." (PMID 36834720, 2023). "In persons with type 2 diabetes, probiotics only slightly decreased HbA1c and fasting insulin levels." (PMID 38022046, 2023). "Thirty two obese Latino male adolescents aged 14–17 years with a family history of type 2 diabetes underwent a frequently sampled glucose tolerance test (FSIVGTT) to measure insulin sensitivity." (PMID 37577670, 2023). "Type 2 diabetes is a condition, characterized by high blood glucose and inadequate response to insulin, called insulin resistance." (PMID 37597078, 2023).
type 2 diabetes (continued). "This compound acts as an anti-inflammatory and anticancer agent and has also been shown to have anti-diabetic properties that can improve insulin sensitivity and decrease blood sugar levels, making it potentially useful in managing Type 2 diabetes." (PMID 37504903, 2023). "In another trial with 62 participants with non-insulin-treated type 2 diabetes, orally administrated cannabidiol in doses of 100 mg twice daily for 13 weeks had no influence on appetite, body mass, or waist circumference." (PMID 37510734, 2023). "Type 2 diabetes mellitus (T2DM) is a prevalent endocrine metabolic condition characterized by impaired insulin sensitivity of peripheral tissue such as the hepatic, muscle, and fatty tissue." (PMID 37957775, 2023). "DHM has been extensively studied in vivo; it reduces thrombus formation induced by FeCl3, and its effects on glycemic control and insulin sensitivity in patients with type 2 diabetes are currently being evaluated in phase II clinical trials (NCT03606694)." (PMID 37438783, 2023). "He pointed out the extraordinary tolerance to insulin in coma and the key role of water, insulin, glucose and alkali in the treatment." (PMID 36585966, 2023). "Adult patients with end-stage renal disease, treated with dialysis, and suffering from type 1 or type 2 diabetes, being treated with insulin, were included in the study." (PMID 37049397, 2023). "Endoplasmic reticulum (ER) stress and beta cell dedifferentiation both play leading roles in impaired insulin secretion in overt type 2 diabetes." (PMID 36280617, 2023). "Ceramides have been reported to regulate the effect of insulin on skeletal muscle and increased levels of ceramide have been reported in obese subjects with type II diabetes." (PMID 37287668, 2023). "Among all enriched disease terms at FDR 5%, many of them are well-supported in the literature such as enrichment of Type-2 Diabetes for Insulin, breast cancer for progesterone, and colorectal cancer for somatotropin." (PMID 37093889, 2023). "This randomized clinical trial found that a VBAI that provided autonomous basal insulin titration improved time to optimal insulin dosing, insulin adherence, and glycemic control among adults with type 2 diabetes compared with standard of care." (PMID 38039007, 2023). "Type 2 diabetes is a lifestyle disease, and all guidelines recommend that insulin therapy should accompany lifestyle modification and oral hypoglycaemic drugs." (PMID 38076524, 2023). "Type 2 diabetes is the most widely occurring category that is characterised by defective insulin secretion and/or action." (PMID 37552330, 2023). "Type 2 diabetes mellitus (T2DM) is a chronic disease in which the body is unable to adequately use the insulin produced in the pancreas." (PMID 36619486, 2023). "Tirzepatide is given to patients with type 2 diabetes after meals to stimulate insulin during both phases of its secretion and concurrently suppresses glucagon release, decreasing blood glucose levels." (PMID 37510690, 2023). "Studies in animal models of obesity and type 2 diabetes have shown that glycine supplementation can reduce white fat and an improve insulin sensitivity." (PMID 38139266, 2023). "It is understood that type 2 diabetes is an immune-mediated condition in which cytokines are crucial for insulin signaling and the eradication of beta cells that produce insulin." (PMID 37575577, 2023). "Optimizing insulin therapy for patients with type 2 diabetes can be challenging given the need for frequent dose adjustments." (PMID 38039007, 2023). "Type 2 diabetes (T2D) is characterized by a progressive deterioration of β‐cell function with a continuous decline in insulin secretion." (PMID 36942376, 2023). "Because the GK rats were selected for highest normal blood glucose levels, it is important to point out that they represent an ideal model of type 2 diabetes with impaired glucose-stimulated insulin secretion attributed to a polygenic inheritance." (PMID 37519334, 2023).
type 2 diabetes (continued). "Repaglinide (RPG), a monotherapy insulin secretagogue used to treat diabetes mellitus-type II yet, it suffers from poor water solubility and variable bioavailability (∼ 50%) due to hepatic first pass metabolism." (PMID 36803255, 2023). "In Type-2 diabetes, the patient becomes insulin resistant, or the insulin produced becomes ineffective at decreasing the high BG levels." (PMID 36766445, 2023). "In studies investigating the glucose-insulin system compared to control groups with similar age and weight, glycemic intolerance, which includes both decreased glucose tolerance and type 2 diabetes, was more common in PCOS women." (PMID 37954695, 2023). "It is a negative regulator of the insulin and leptin signaling pathways and is found to be a promising prospective therapeutic target, particularly for type 2 diabetes treatment." (PMID 37894680, 2023). "On the basis of the growing evidence, its use is currently recognized as the standard of care for people with type 1 diabetes and for a subset of those with insulin-requiring type 2 diabetes." (PMID 37676398, 2023). "In a study of patients with type 2 diabetes, Orlistat improved insulin concentration after six months." (PMID 37420181, 2023). "Altogether, these data suggest that dysregulated AQP7 expression is linked to dysregulated insulin secretion, thereof suggesting AQP7 as a potential therapeutic target for human obesity-associated type 2 diabetes." (PMID 37681902, 2023). "We performed two-sample MR using external studies of type 2 diabetes, and oral and intravenous measures of insulin secretion and sensitivity." (PMID 37280435, 2023). "Fasting serum insulin is an important marker for metabolic disorders, including obesity, type 2 diabetes and the metabolic syndrome." (PMID 37420130, 2023). "The INSR is an important protein in the insulin signaling pathway and has been reported to be abnormally expressed in the muscles and adipocytes of obese, insulin-resistant, and type 2 diabetic patients." (PMID 36834919, 2023). "PTP1B plays a fundamental role in controlling glucose uptake and insulin regulation, making it a promising therapeutic target for type 2 diabetes." (PMID 37047505, 2023). "It was reported that HIIT exercises for 8 weeks were shown to improve glycemic control and pancreatic β Cell function, preserve insulin secretion, and enhance insulin sensitivity of type 2 diabetes." (PMID 37512131, 2023). "In a previous study, we achieved euglycemia by eliminating glucose in urine by adding SGLT2i and reduced the time required to achieve euglycemia for the management of insulin-treated type 2 diabetes." (PMID 36804863, 2023). "Patients with type 2 diabetes and reduced insulin secretion have previously been shown to respond less well to noninsulin antihyperglycemic agents." (PMID 37589043, 2023). "Is the stepping-down approach a better option than multiple daily injection in obese patients with poorly controlled type 2 diabetes on advanced insulin therapy?" (PMID 37101024, 2023). "Some studies reported that hepatic insulin clearance was decreased in patients with type 2 diabetes." (PMID 38115089, 2023). "Glucose and insulin concentration rose faster in healthy and type 2 diabetic patients when RDS was digested than when SDS was digested." (PMID 37238882, 2023). "Insulin is the primary treatment for type 1 and some type 2 diabetes but remains costly in the United States, even though it was discovered more than a century ago." (PMID 37971985, 2023). "SGLT2 inhibition in type 2 diabetic patients reduces hyperglycemia and improves insulin secretion from beta cells and peripheral insulin sensitivity." (PMID 37108143, 2023). "Compared to individuals with type 2 diabetes, those with LADA, and particularly LADAhigh, had lower HOMA-IR and HOMA-B and were more likely to be treated with insulin and have a high-risk HLA genotype." (PMID 37299509, 2023).